CAMK2A (calcium/calmodulin dependent protein kinase II alpha)
Description:
Calcium/calmodulin-dependent protein kinase that functions autonomously after Ca(2+)/calmodulin-binding and autophosphorylation, and is involved in various processes, such as synaptic plasticity, neurotransmitter release and long-term potentiation. Member of the NMDAR signaling complex in excitatory synapses, it regulates NMDAR-dependent potentiation of the AMPAR and therefore excitatory synaptic transmission (By similarity). Regulates dendritic spine development. Also regulates the migration of developing neurons. Phosphorylates the transcription factor FOXO3 to activate its transcriptional activity. Phosphorylates the transcription factor ETS1 in response to calcium signaling, thereby decreasing ETS1 affinity for DNA (By similarity). In response to interferon-gamma (IFN-gamma) stimulation, catalyzes phosphorylation of STAT1, stimulating the JAK-STAT signaling pathway. In response to interferon-beta (IFN-beta) stimulation, stimulates the JAK-STAT signaling pathway. In response to interferon-gamma (IFN-gamma) stimulation, catalyzes phosphorylation of PSAT1, inhibiting ferroptosis by promoting GPX4 hydroxylation and stability. Acts as a negative regulator of 2-arachidonoylglycerol (2-AG)-mediated synaptic signaling via modulation of DAGLA activity (By similarity).
Synonyms: CAMKA; KIAA0968; CaMKIINalpha; CaMKIIα; CaMKIIalpha; MRD53; MRT63
Tractability: Small molecule: a structure with a bound ligand is known; a high-quality ligand is known; it has a high-quality binding pocket; it belongs to a druggable protein family. PROTAC: ubiquitination databases record sites on it; its protein half-life has been measured; a small molecule that binds it is known.
Target class: CAMK protein kinase CAMK2 family; Protein Kinase; Enzyme; CAMK protein kinase group; Kinase
Safety:
Unwanted effects reported when the protein is acted on. In parentheses: how it was acted on, where the effect was seen, and who reports it.
heart disease (cardiovascular system; source: Force et al. (2011))
Gene: Protein-coding gene on chromosome 5 (150,219,491 to 150,290,093, reverse strand). Ensembl gene ENSG00000070808.
Subcellular location: Synapse; Postsynaptic density; Cell projection, dendritic spine; Cell projection, dendrite
Subcellular location (Human Protein Atlas): Plasma membrane; Primary cilium tip; Primary cilium transition zone; Principal piece; Calyx; Cell Junctions; Connecting piece; End piece; Perinuclear theca
Pathways (Reactome):
Disease: Dengue Virus-Host Interactions; Paradoxical activation of RAF signaling by kinase inactive BRAF; Signaling by BRAF and RAF1 fusions; Signaling by RAF1 mutants; Signaling by moderate kinase activity BRAF mutants; Signaling downstream of RAS mutants
Neuronal System: Assembly and cell surface presentation of NMDA receptors; Long-term potentiation; Negative regulation of NMDA receptor-mediated neuronal transmission; Ras activation upon Ca2+ influx through NMDA receptor; Trafficking of AMPA receptors; Unblocking of NMDA receptors, glutamate binding and activation
Signal Transduction: Ca2+ pathway; CaMK IV-mediated phosphorylation of CREB; RAF activation; RAF/MAP kinase cascade
Muscle contraction: Ion homeostasis; Phase 0 - rapid depolarisation
Cellular responses to stimuli: HSF1-dependent transactivation
Immune System: Interferon gamma signaling
Transport of small molecules: Ion transport by P-type ATPases
Gene Ontology:
Molecular function: calcium/calmodulin-dependent protein kinase activity; calmodulin binding; identical protein binding; protein binding; protein homodimerization activity; protein serine kinase activity; protein serine/threonine kinase activity; glutamate receptor binding; ATP binding; protein kinase activity
Biological process: angiotensin-activated signaling pathway; cellular response to interferon-beta; cellular response to type II interferon; dendritic spine development; negative regulation of ferroptosis; positive regulation of canonical NF-kappaB signal transduction; positive regulation of receptor signaling pathway via JAK-STAT; regulation of neuron migration; calcium ion transport; G1/S transition of mitotic cell cycle; long-term synaptic potentiation; positive regulation of calcium ion transport; positive regulation of cardiac muscle cell apoptotic process; regulation of endocannabinoid signaling pathway; regulation of mitochondrial membrane permeability involved in apoptotic process; regulation of neuronal synaptic plasticity; regulation of neurotransmitter secretion; regulation of protein localization to plasma membrane; response to ischemia
Cellular component: calcium- and calmodulin-dependent protein kinase complex; dendritic spine; nucleus; cytoplasm; cytosol; endocytic vesicle membrane; endoplasmic reticulum membrane; mitochondrion; neuron projection; nucleoplasm; postsynaptic density; synapse; dendrite; Schaffer collateral - CA1 synapse
Genetic constraint (gnomAD): Loss-of-function variants: 7 observed, 70.34 expected, observed/expected ratio (o/e) 0.0995, 90% interval 0.056 to 0.19. The upper end of that interval is the gene's LOEUF score, 0.19, which puts it in group 1 of 6, group 1 being the genes least tolerant of losing a copy. Missense variants: 204 observed, 620.97 expected, observed/expected ratio (o/e) 0.33, 90% interval 0.29 to 0.37. Synonymous variants: 233 observed, 246.78 expected, observed/expected ratio (o/e) 0.94, 90% interval 0.85 to 1.05.
Gene-disease validity (ClinGen):
ClinGen rates the evidence that CAMK2A causes each of these diseases.
complex neurodevelopmental disorder (autosomal dominant): Definitive. A disorder that involves more than one phenotype associated with the central nervous system, including but not limited to intellectual disability, autism, and seizures (epilepsy).
Homologues: Orthologues: chimpanzee CAMK2A (100% identical), guinea pig CAMK2A (99% identical), mouse Camk2a (99% identical), pig CAMK2A (99% identical), rat Camk2a (99% identical), dog CAMK2A (98% identical), tropical clawed frog camk2a (97% identical), rabbit CAMK2A (96% identical), zebrafish camk2a (92% identical), macaque CAMK2A (92% identical). Paralogues in human: CAMK2D (86% identical), CAMK2B (84% identical), CAMK2G (83% identical), CAMK1G (29% identical), CAMK1 (29% identical), CAMK1D (28% identical), DCLK2 (27% identical), DCLK1 (27% identical), PNCK (27% identical), PHKG2 (26% identical), PHKG1 (25% identical), CAMKK1 (25% identical), and 10 more.
Diseases named in the same sentence as CAMK2A in open-access papers:
CAMK2A is named in the same sentence as 142 diseases in open-access papers, as found by Europe PMC text mining. Sharing a sentence is not in itself a finding about the gene and the disease. The quoted sentences say what the papers report.
Anxiety (41 papers, 2011 to 2026). Intense feelings of nervousness, tension, or panic often arise in response to interpersonal stresses. "Among Camk2a+/− mice, we previously showed that levels of infradian oscillatory LA in the home cages were associated with anxiety-like and depression-like behaviors." (PMID 31822292, 2019). "In this study, Camk2a expression was elevated in the hypothalamus of E2-treated mice and positively associated with open-arm entries in the elevated plus maze, suggesting a role in neural plasticity and anxiety-related behaviors." (PMID 40427344, 2025). "For example, Ube3a overexpression in Camk2a-positive neurons resulted in anxiety-like behaviors, learning impairments, and reduced seizure thresholds (but not social deficits or repetitive behaviors)." (PMID 38996019, 2024). "To examine the role of MRs in anxiety and memory formation we used transgenic mice with forebrain specific overexpression of human MR under the control of a calcium/calmodulin-dependent protein kinase II alpha (CaMKIIα) promoter." (PMID 26236208, 2015). "Previous studies testing the role of Htr1a hetero-receptors on anxiety either used expression of Htr1a under control of the Camk2a promoter on an otherwise knockout background or used the suppression of endogenous Htr1a in Camk2a-expressing cells." (PMID 25759645, 2015). "Importantly, changes in the LA were correlated with changes in depression-like and anxiety-like behaviors, suggesting that Camk2a+/− mice are useful as an animal model which shows similar infradian oscillations of mood to those found in patients with bipolar disorder." (PMID 31822292, 2019). "Similarly, it has been shown that overexpression of Camk2a leads to increased anxiety in mice." (PMID 27625594, 2016). "Because our Cdc42f/f: Camk2a-Cre mice showed defects in the synaptic plasticity and reduction of dendritic spines in the hippocampus, we hypothesized the Cdc42 cKO mice might exhibit an anxiety phenotype." (PMID 25006034, 2014). "Since absence of Crh specifically in GABAergic, Camk2a-expressing CRH neurons increased anxiety, we wondered whether deletion of the neuropeptide from the entire GABAergic forebrain population would produce a similar or distinct phenotype." (PMID 31619956, 2019).
Cognitive impairment (22 papers, 2018 to 2026). Abnormal cognition is characterized by deficits in thinking, reasoning, or remembering. "The concurrent downregulation of both Camk2a and Camk2g may therefore contribute to cognitive deficits associated with cerebellar dysfunction." (PMID 41150532, 2025). "Notably, human-specific miR-137 targets, such as CAMK2A, known to be linked to cognitive impairments and NDD, exhibited dysregulation in MIR137-/- miniature pigs." (PMID 38937838, 2024). "Seven differentially expressed autoantibodies were recognised as cognitive impairment-related, including HSPD1, CDK19, TKT, BRSK2, NRAS, LMNA, and CAMK2A." (PMID 38107644, 2023). "Camk2a-tTA;TRE-hShh normalized locomotor hyperactivity and improved learning and memory in 3-month-old Ts65Dn, mitigated early-onset severe cognitive impairment in 7-month-old Ts65Dn, and enhanced spatial cognition in euploid mice." (PMID 34399854, 2021).
depression (22 papers, 2015 to 2025). "The overlapping genes in these activation pathways were Camk2a and calcium/calmodulin-dependent protein kinase II delta (Camk2d), which have been linked to the development of depression." (PMID 37505566, 2023). "The gene of CAMK2A has been reported to be associated with depression, and the expression of CAMK2A was significantly elevated in the depression tissues by 29%." (PMID 34306154, 2021). "Downregulation of synaptic genes like Syn1, Rab3a, Camk2a, Nrxn2 have been strongly associated with major depression." (PMID 29743870, 2018). "GATA1 is known to repress transcription of synaptic genes like Syn1, Camk2a, and Rab3a, and associated with Major Depressive Disorder in human patients." (PMID 29743870, 2018). "Selective Bmal1KO in CaMK2a excitatory neurons revealed that the functional mPFC clock is an essential factor for the development of a depression-like phenotype and ketamine effects." (PMID 39179578, 2024). "We computed the up-regulation network using the Cytohubba plugin in Cytoscape and found that both Camk2a and Camk2d were on major nodes of the up-regulated ceRNA network mRNA, suggesting that Camk2a and Camk2d play an active role in depression." (PMID 37505566, 2023). "In another study, calcium/calmodulin-dependent protein kinase II Alpha (Camk2a) played a significant role in the development of depression." (PMID 37505566, 2023). "Our SH-SY5Y-derived CaMK2A model is an appropriate system to study the associations of synaptogenesis, LTP, and long-term depression and the cognitive function of students." (PMID 34607601, 2021). "To see whether camk2a-Hap1 KO mice would behave similarly in the depression tests as the induced Hap1 KO mice, we performed the FST and TST, which demonstrated that camk2a-Hap1 KO mice at 2-month old indeed displayed depressive-like behavior." (PMID 25875952, 2015). "Therefore, HF may improve depression symptoms by regulating including but not limited to MAOA, MAOB, AR, CAMK2A, and GAD2." (PMID 34306154, 2021). "To rule out the possibility that our Hap1 KO mice had any physical impairment that might result in poor performances in depression tests, as well as a locomotor activity assay, we did a rotarod test on both P1 KO and camk2a-Hap1 KO mice; we found no such impairment in either of the KO groups." (PMID 25875952, 2015).
schizophrenia (18 papers, 2013 to 2025). A major psychotic disorder characterized by abnormalities in the perception or expression of reality. "In cortical and hippocampal Camk2a neurons, we identified signature proteins linked to epilepsy (e.g., Dlg4) and schizophrenia (e.g., Grin2a)." (PMID 35614064, 2022). "Camk2a has been implicated in a number of psychiatric diseases including autism, schizophrenia and addiction." (PMID 34198070, 2021). "Interestingly, regional differences in phospholipase C isoenzyme (Plcb1, Plcb4), druggable targets identified in the Camk2a proteome, expression in the brain are known to underlie several brain disorders including epilepsy, schizophrenia, and AD47." (PMID 35614064, 2022). "Intriguingly, a recent genetic study identified nonsense mutations within CAMK2A gene in patients with schizophrenia, further supporting possibility of CaMKII as an indispensable molecule to mediate pathophysiological conditions of schizophrenia." (PMID 29610762, 2018). "Indeed, group 3 cdDMRs were present in genes such as GRIN1, SYN1, and CAMK2A, and others involved in establishing synapse organization and function, a hallmark of early postnatal brain development, implicating abnormal genetic regulation of neuronal connectivity in schizophrenia development." (PMID 31554518, 2019). "The molecules that mostly contributed to discriminate schizophrenia from controls were EAAT2, CAMK2A, Synapsin-1, l-Asn, GRIA2, GRIA4, and SLC17A7 whereas the ones that barely contributed to the discrimination were: Gly, mGluR5, CaMKIIα, VGluT1, and d-Asp." (PMID 35217646, 2022). "In the hippocampus, subjects with CAMK2A expression < 0.79 and (at the same time) with GRIA2 expression < 0.64 achieved 95% chance of having the schizophrenia whereas those with CAMK2A expression ≥ 0.79 and EAAT2 ≥ 37 % were more likely to do not have the disease at all (probability of 0%)." (PMID 35217646, 2022).
epilepsy (15 papers, 2013 to 2025). A brain disorder characterized by episodes of abnormally increased neuronal discharge resulting in transient episodes of sensory or motor neurological dysfunction, or psychic dysfunction. "It regulates the synthesis of calcium/calmodulin dependent protein kinase II alpha (CaMKIIα) that influences synaptic plasticity, the expression of multiple ion channels and can lead causes epilepsy in knock-out mutant mice." (PMID 27855659, 2016). "Finally, this conclusion is supported by gene therapy studies targeting excitatory neurons with a Camk2a promoter, showing reduced seizures in models of epilepsy." (PMID 37511107, 2023).
Intellectual disability (11 papers, 2018 to 2025). "For example, human orthologs to fly genes CASK (CASK), Mnb (DYRK1A), Dlg-1 (DLG1), Cdc42 (CDC42), Fmr1 (FMR1, FXR1/2), trio (TRIO), Nedd4 (NEDD4L/NEDD4) and CamKII (CAMK2A/B/D) have been linked to intellectual disability." (PMID 37759179, 2023). "Later, de novo heterozygous mutations in the CAMK2A gene were reported in individuals affected by intellectual disability of variable degrees." (PMID 37510258, 2023). "In this report, we describe a thirty-five-year-old woman severely affected by intellectual disability and epilepsy, with a novel mutation in the CAMK2A gene." (PMID 37510258, 2023). "In keeping with this, molecular phenotyping of other reported CAMK2A de novo mutations linked to intellectual disability revealed aberrant facilitation of Ca2+/CaM-dependent activation of CaMKIIα in most cases." (PMID 36117912, 2022). "In this study, we report a new case of CAMK2A P212L, a recurrent mutation, in a patient with an intellectual disability." (PMID 36117912, 2022). "In summary, we have identified an autosomal recessive neurodevelopmental syndrome characterized by growth delay, frequent seizures and severe intellectual disability that is caused by a biallelic germline loss-of-function mutation in CAMK2A." (PMID 29784083, 2018). "Quantitative analysis showed increased expression of all examined genes with the most significant changes for known intellectual disability genes CAMK2A and FMR1." (PMID 34946860, 2021). "Recently, it has been reported that de novo mutations in the protein kinase genes CAMK2A and CAMK2B cause intellectual disability and neurodevelopmental disorders." (PMID 32560273, 2020). "Our patient phenotype perfectly matches with that of other patients carrying CAMK2A pathogenic variants; shared phenotypic traits include severe intellectual disability, seizures, microcephaly, absent speech, developmental and motor delay." (PMID 37510258, 2023). "Moreover, it dysregulated other genes linked to intellectual disability, such as FMR1, SYN1, CAMK2A, and THOC2." (PMID 34946860, 2021). "Finally, the pharmacological reversal of CAMK2A P212L phenotype in neurons was demonstrated using an FDA-approved NMDA receptor antagonist memantine, providing a basis for targeted therapeutics in CAMK2A-linked intellectual disability." (PMID 36117912, 2022). "Following the reduced expression level of CAMK2B, a compensatory increase in CAMK2A expression can counteract this decline, exemplified by the impact of CAMK2A and CAMK2B deletion on brain neurodevelopment, ultimately leading to intellectual disability." (PMID 41050075, 2025).